EGF (epidermal growth factor)
Diseases named in the same sentence as EGF in open-access papers (continued):
Sharing a sentence is not in itself a finding about the gene and the disease.
breast carcinoma (continued). "The HS578T-Hyg breast cancer cells and M13HS-1 hybrid cells exhibited a similar migratory phenotype, and the EGF-induced migration was attributed to both an enhanced number of moving cells as well as an increased time of active movement." (PMID 28768501, 2017). "The screen was performed in the MDA-MB-468 breast cancer cell line, which exhibits epithelial mesenchymal plasticity and can be induced to undergo reversible EMT with EGF or hypoxia in vitro." (PMID 27876705, 2016). "In conclusion, EGF-induced EMT via phospho-Smad2/3-Snail pathway was a crucial event during the migration and invasion of MCF-7 and MDA-MB-231 breast cancer cells." (PMID 27829223, 2016). "Protein tyrosine phosphatase, non-receptor type 9 (PTPN9) is a soluble tyrosine phosphatase that attenuates prolactin- and EGF-mediated STAT5 activation, which regulates expression of genes that promote cell survival and proliferation in breast cancer cells." (PMID 27472371, 2016). "EGF also induced EMT and invasion of MDA-MB-231 breast cancer cells through ERK1/2-phospho-Smad2/3-Snail signaling pathway." (PMID 27829223, 2016). "In MCF-7 breast cancer cell line, HRG has been shown to increase a sustained mitogen-activated protein kinase (MAPK) signal activity favoring differentiation, whereas EGF only elicits a transient MAPK signal activity favoring cell proliferation." (PMID 26716646, 2016). "Through these selective, regulated interactions Lamellipodin mediates directional sensing of epidermal growth factor (EGF) gradients and invasive 3D migration of breast cancer cells." (PMID 26996666, 2016). "We found that EGF/ERBB signaling genes made up a larger proportion of cancer signaling genes in GBM and Her2 breast cancer signaling pathways, compared with those in the Wnt-β-catenin signaling pathway." (PMID 27910913, 2016). "When activated by leptin or estrogen in breast cancer cells, STAT5 requires c-Src and epidermal growth factor (EGF)." (PMID 27472371, 2016). "In MDA-MB-468 breast cancer cells, SOCE is involved in EGF-induced epithelial-mesenchymal transition, and EGF-mediated cell growth requires Orai1 and STIM1 in ARPE-19 cells." (PMID 26919241, 2016). "IL-1β induced IL-6 production in breast cancer cells in a TG2-dependent manner, and other cytokines and growth factors including TGF-β, TNF-α, and EGF potentiated the effect of IL-1β on IL-6 expression." (PMID 27609180, 2016). "In MCF-7 and MDA-MB-231 human breast cancer cell lines, both LPA and EGF stimulated proliferation, Erk activation, Akt activation, and CCN1 induction." (PMID 26821052, 2016). "Treatment with TGF-β, EGF, and TNF-α after IL-1β further increased IL-6 expression in MCF7_TG2 breast cancer cells." (PMID 27609180, 2016). "EGF up-regulates PADI2 transcription and translation in CMT25 cells, a canine mammary tumor cell line." (PMID 27478411, 2016). "Here, we used human breast cancer cell lines MCF-7 and T47D to examine the effects of EGF on E-cadherin internalization." (PMID 25678857, 2015). "It is well established that the endogenous synthesis of insulin-like growth factor (IGF) and epidermal growth factor (EGF) polypeptide growth factors are closely correlated to malignant transformation and all the steps of the breast cancer metastatic cascade." (PMID 26258011, 2015). "In this study, we illustrate a molecular signaling cascade in which the EGF-Src-β4 integrin axis physically recruits and activates FAK activity and downstream signaling, thereby facilitating the progression of breast cancer towards malignancies." (PMID 26549523, 2015). "Specifically, we found that PYK2 is activated in response to EGF and HRG in different breast cancer subtypes and that PYK2 depletion leads to substantial inhibition of EGF/HRG-mediated cell spreading, migration and invasion." (PMID 26084289, 2015). "Previous studies have shown that EGF and HRG enhance the migration of these three breast cancer cell lines, as well as the invasion of MCF7 and SKBR3 cells." (PMID 26084289, 2015).
breast carcinoma (continued). "Knockdown of Anxa2 also impaired EGF-induced EMT, as well as breast cancer cell invasion in vitro and metastatic potential in vivo." (PMID 26307676, 2015). "In conclusion, our data demonstrate that TGF-β1 induces EMT by the transactivation of EGF signaling through HA/CD44 in lung and breast cancer cells." (PMID 26005723, 2015). "The HA-CD44-mediated TGF-β1 and EGF signaling, and the co-localization of CD44/EGFR had an effect on the activation of EGF signaling induced by TGF-β1 in lung and breast cancer cells." (PMID 26005723, 2015). "Previously, we reported that EGF-inducible phosphorylation of Crk on Tyr251 resulted in the transactivation of Abl kinase, and affirmatively regulated cell motility in MDA-MB-468 breast cancer cell lines." (PMID 26473374, 2015). "While only in a single breast cancer cell line, we demonstrate the potential for progesterone to activate EGFR signalling, consistent with progesterone potentiation of EGF responses in ZR-75-1 cells." (PMID 26498662, 2015). "In this study we chose two cytokines important in our breast cancer model and verified interaction with CXCL447–70 and CXCL4L147–70: EGF as growth factor for the tumor cells and CCL5 as attractant of monocytes/macrophages." (PMID 25373734, 2014). "A complex variety of cytokines and growth factors such as TGF-β, hepatocyte growth factor (HGF), epidermal growth factor (EGF), and tumour necrosis factor α (TNFα) have been shown to influence MMP 9 induction by fibroblasts in breast cancer cells." (PMID 24800085, 2014). "EGFR binding (F10) is mediated through the binding of a mitogenic peptide epidermal growth factor (EGF) to a surface membrane receptor, EGFR of breast cancer cells." (PMID 24997799, 2014). "For instance, a reciprocal interaction exists between macrophages and breast cancer cells whereby the tumor cells produce CSF1 and express the receptor for EGF while macrophages produce EGF and express the receptor for CSF1." (PMID 25313137, 2014). "Further, Giα proteins can differentially regulate the activation of Akt, mTORC1 and ERK1/2 by EGF, bFGF and IGF-1 in breast cancer cells." (PMID 24521094, 2014). "Recently, Brk was shown to mediate EGF-induced activation of MAPK, which contributes in part to the proliferation and migration of breast cancer cells in response to these growth factors." (PMID 24736807, 2014). "The regulatory role of PTPD1 on EGF signalling, and the pathological role of over expressed EGFR during breast carcinogenesis and metastasis, makes breast cancer an interesting model for studying PTPD1 dynamics." (PMID 25062045, 2014). "Pharmacological compounds can induce apoptosis in lung and breast cancer cells by inhibiting the EGFR pathway, and recent work has demonstrated that Mig-6 actively senses EGF deprivation to directly activate proapoptotic c-Abl in murine epithelial cells." (PMID 24670222, 2014). "By taking this general approach of Ras hyper-activation, we have recapitulated the excessive activation of the Ras pathway in breast cancer, which is induced in patients by multiple RTK ligands such as epidermal growth factor (EGF)." (PMID 24598028, 2014). "SPA inhibited EGF-dependent mitogenesis, as indicated by a relative large reduction in positive Ki-67 staining in MDA-MB-231 breast cancer cells." (PMID 24736807, 2014). "Here, we dissect the pathways used by highly metastatic breast carcinoma cell line MDA-MB-231, which are able to migrate and invade toward LPA, HGF and EGF." (PMID 24160245, 2013). "Several studies demonstrate that the expression of EGF and EGFR is related with breast cancer growth, progression and aggressiveness and its overexpression is an indicative of poor prognosis." (PMID 24138843, 2013). "Epidermal growth factor- (EGF-) mediated signaling is one of the most important signaling pathways for cell growth, proliferation, invasion, and metastasis in breast cancer." (PMID 23431444, 2013).
breast carcinoma (continued). "Apart from its anti-EGF and VEGF effect in inhibiting tumor cells, it can also inhibit metastasis and spread of breast cancer cells by inhibiting MMP." (PMID 24138843, 2013). "There is considerable evidence for a role of EGF in promoting breast cancer cell invasion, and we have shown that BCAR3 can regulate the migration/invasion of breast tumor cells toward EGF." (PMID 23762409, 2013). "EGF, which activates both AKT and MAPK pathways, plays an important role in both ovarian and breast cancer pathophysiology." (PMID 25520884, 2013). "In breast cancer cells Rac1 is a downstream effector of ErbB receptors and mediates migratory responses by ErbB1/EGFR ligands such as EGF or TGFα and ErbB3 ligands such as heregulins." (PMID 23533813, 2013). "Klf4 expression was also found reduced in human breast cancer cell lines, such as in SKBR3 upon EGF-induced EMT and in MCF7 cells which undergo EMT upon stable depletion of E-cadherin." (PMID 23451207, 2013). "Stimulation of the human breast cancer MCF-7 cell line with EGF resulted in a rapid induction of TTP expression, the maximal effect being observed 30 minutes after EGF treatment." (PMID 22433566, 2012). "Collectively, our data underscore the pivotal role of P4 and EGF signaling cross-talk as well as the impact of PRA/PRB ratio for controlling key target genes such as HBEGF and AREG involved in breast cancer development and metastasis." (PMID 23029355, 2012). "We also show that mammosphere cultures of epithelial-like breast cancer cells, T47D, MCF7, ZR-75-1 and MDA-MB-453 cells, consistently generated stem-like cancer cells solely as a result of the EGF and bFGF cytokines in the mammosphere media mediating EMT." (PMID 22134360, 2012). "In breast cancer cells, RGS16 reduced epidermal growth factor (EGF)-evoked proliferation by inhibiting PI3K signalosome formation." (PMID 22253691, 2012). "Indeed, EGF-induced EMT in MDA-MB-468 breast cancer cells is associated with a remodeling of purinergic receptor-mediated Ca2+ signaling and transforming growth factor β (TGFβ)-induced EMT in MCF7 breast cancer cells has been reported to be associated with increased store-operated Ca2+ influx." (PMID 22666335, 2012). "We found that overexpression of EBP50 inhibited EGF-induced breast cancer MDA-MB-231 cell proliferation, whereas knockdown of EBP50 enhanced EGF-induced breast cancer MCF-7 cell proliferation." (PMID 22476347, 2012). "Overall, these results indicate that EGF is a potent regulator of HIF-1α expression in normoxic PyMT mammary tumor cells, as previously observed in SK-BR-3 and MCF-7 cells, and that EGF prolongs HIF-1α stabilization under hypoxic conditions." (PMID 22225988, 2012). "This demonstrated that EGF, like Kp-10, induces the internalization of GPR54 in breast cancer cells." (PMID 21738726, 2011). "Cancer cells are dependent upon extracellular cues from the tumor microenvironment, such as epidermal growth factor (EGF), which can promote breast cancer cell migration." (PMID 21850275, 2011). "The late gene network is centered on ERBB2, a member of the epidermal growth factor (EGF) family of receptor tyrosine kinases, and one of the major molecular prognostic and predictive markers in breast cancer." (PMID 21878096, 2011). "We also found that EGF treatment promoted the internalization of GPR54 in breast cancer cells and that GPR54 and EGFR partially co-localized upon treatment of Kp-10 or EGF." (PMID 21738726, 2011). "In this study, which will be referred to here as the HER2 dataset, the authors were interested in the signaling response downstream of EGF and HRG and in response to HER2 amplification, which is common to several breast cancers." (PMID 21799663, 2011). "The induction of the tyrosine kinase activity by epidermal growth factor (EGF) and consequentially increased MDR gene expression has been discussed previously in breast cancer cells." (PMID 22088142, 2011).
breast carcinoma (continued). "Many studies suggest that MYH9/NMHC-IIA has a key role in tumor cell invasive behavior.For example, the EGF-dependent phosphorylation of the myosin-IIA heavy chain has a direct role in mediating motility and chemotaxis in MDA-MB-231 human breast cancer cells." (PMID 21533124, 2011). "For instance, some tumor cells within breast cancer are known to stimulate their clonemates via secreted factors such as lysophosphatidic acid (LPA) and epidermal growth factor (EGF)." (PMID 21619636, 2011). "EGF induces nucleolar translocation of HPSE and induction of DNA topoisomerase I which is essential for BM from breast cancer and cell proliferation." (PMID 22567347, 2011). "Exogeneous overexpression of HER2 or stimulation by EGF and NRG1 of different breast cancer cell lines induce the up-regulation of hMena both at the mRNA and protein levels, which suggests a link between ErbB family activation and hMena." (PMID 21209853, 2010). "We previously identified an important role for Brk in EGF- and heregulin- induced ERK5 activation in T47D breast cancer cells." (PMID 20687930, 2010). "Low EGF concentrations in a low serum-containing medium stimulated growth of high ERα-expressing human breast cancer cell lines A431 and BT20, while high EGF doses inhibited their growth." (PMID 20809984, 2010). "Over-expression of EGF and its receptor (EGFR) has been found in many human tumors and cell lines, including breast cancer." (PMID 21079779, 2010). "We previously showed that Brk is required for EGF- and heregulin-induced activation of ERK5 and p38 MAPK in breast cancer cells." (PMID 20687930, 2010). "Data presented here indicate the ability of hMena/hMena11a to sustain EGF and NRG1-mediated signalling responsible for a proliferative signature of breast cancer." (PMID 21209853, 2010). "nEASE analysis also suggests that GIPC1 is involved in six major signal transduction networks in breast cancer: integrin-mediated, RHO protein, JAK-STAT, EGF, TGFβ and WNT." (PMID 21209904, 2010). "The epidermal growth factor (EGF) receptor gene (EGFR/HER1/ERBB1) and other EGF receptors (HER2/NEU/ERBB2, HER3 and HER4) are frequently expressed in human breast cancer cells, including MDA-MB-231 cells." (PMID 21029421, 2010). "Serum concentrations of epidermal growth factor, soluble CD40-ligand and proapolipoprotein A1 were increased in breast cancer patients." (PMID 19400944, 2009). "Crosslinking α6β4 integrin in breast carcinoma cells induces EGFR clustering and preferentially promotes Rho activation in response to EGF, with only minimal effects on Akt and Erk 1,2 phosphorylation." (PMID 19470173, 2009). "In MCF-7 breast cancer cells, HRG can elicit differentiation while treatment of cells with EGF leads to cell proliferation, processes which possess different intensities of signaling and gene regulation that work in a coordinated manner." (PMID 19925682, 2009). "Among these candidates, miR-125a-5p appeared to be particularly intriguing, because its level was altered most significantly by EGF stimulation, and it has been shown that miR-125a regulates the phosphorylation of ERK1/2 and Akt in breast cancer cells." (PMID 19702827, 2009). "Crosslinking α6β4 integrin in breast carcinoma cells induces EGFR clustering and preferentially promotes Rho activation in response to EGF." (PMID 19470173, 2009). "We observed that EGF treatment was followed by increased translocation of Jab1 to the nucleus in both MDA-MB-231 and MDA-MB-468 breast cancer cell lines." (PMID 18534028, 2008). "EGF and its related family member, HER2/Neu, are commonly expressed in breast cancers, including in 60% of invasive breast cancers." (PMID 18320059, 2008).
breast carcinoma (continued). "In these studies 17β-oestradiol and EGF induced increased cell proliferation in both ER-positive MCF-7 and ER-negative SKBR3 breast cancer cell lines." (PMID 16805920, 2006). "The angiotensin II receptor competitive inhibitor saralasin attenuated the proliferative effects of 17β-oestradiol and EGF in SKBR3 and MCF-7 breast cancer cells, in a similar manner to that seen for pertussis toxin." (PMID 16805920, 2006). "Of interest, treatment with pertussis toxin also abrogated the cell growth and Raf phosphorylation seen in the presence of EGF and EGF in combination with 17β-oestradiol, in particular in ER-positive MCF-7 breast cancer cells." (PMID 16805920, 2006). "We first examined the modulation of breast cancer cell survival in the presence of IGF-I, IGF-II, FGF-2 or EGF, and we confirmed that, except for EGF, these growth factors promoted MCF-7 and T47D cell survival in vitro under serum-free conditions." (PMID 12838321, 2003). "The spontaneous expression of HLA class I and class II molecules in two human breast carcinoma cell lines (MCF7, T47D) and their modulation during epidermal growth factor treatment are reported." (PMID 1637682, 1992). "EGF treatment also increases the basal ECAR in glioblastoma cells, as well as the lactate production and both basal and maximal ECAR in breast cancer cells." (PMID 39433211, 2025). "For example, when stimulated with EGF, PLSCR1 not only directly binds to the promoter of STAT1, but also enhances STAT3’s binding to the STAT1 promoter in breast cancer cells, leading to the transactivation of STAT1 and basal-like breast cancer (BLBC) progression." (PMID 40248364, 2025). "Notably, the current study reveals a new role of Nuclear Protein 1 (NUPR1/P8/COM1) in regulating the expression of HDAC5, ERBB2 (and the survival reliance switch from estrogen to EGF) and BIRC5 (a well-known oncogene) in breast cancer cells." (PMID 39991577, 2025). "TGM2 expression was also increased in MCF7 (breast cancer), DU145 (prostate cancer), and A549 (lung cancer) cell lines in response to two other EMT-inducers TNFα and EGF, demonstrating that increased TGM2 expression is consistently associated with the EMT process." (PMID 40777010, 2025). "By stimulating breast cancer cells with growth factors released by endothelial cells, such as EGF or TGFβ, we found that EGF, but not TGFβ, can lead to breast cancer cell elongation compatible with extravasation." (PMID 38762624, 2024). "For example, the increased expression of TGase2 (TG2) and subsequent activation of NF-κB has been shown to contribute to drug resistance in breast cancer cells independent of EGF signaling." (PMID 39654623, 2024). "Additionally, in an EGF-induced EMT model, ZN444B impaired the ability of breast cancer cells to undergo EMT." (PMID 39010083, 2024). "For instance, TSPAN8 knockdown attenuated the effects of EGF on gastric cancer cell proliferation and invasion, while the suppression of endogenous EGF expression by KDM2A, a histone demethylase, decreased TSPAN8 expression in breast cancer cells." (PMID 38275818, 2024). "YTHDC1 binds to m6A-modified EGF mRNA and promotes EGF synthesis, suggesting that METTL3 and YTHDC1 together enhance HR and cell survival during doxorubicin treatment, leading to the development of drug resistance in breast cancer." (PMID 37264402, 2023). "AP-1, in combination with EGF signalling, plays an essential role in regulating the transcriptional programme of SMAD and promotes TGF-β-induced invasiveness by cooperating with SMAD in the ΔNp63-expressing breast cancer cell lines." (PMID 37439249, 2023). "In a recent study, carotenoid NE produced a prominent antiproliferative effect in breast cancer cells (MCF-7) and tumor-bearing mice by virtue of considerable reduction in epidermal growth factor (EGF) and vascular endothelial growth factor (VEGF) levels compared to the carotenoid extract." (PMID 37958750, 2023).